RETN (resistin)
Diseases named in the same sentence as RETN in open-access papers (continued):
Sharing a sentence is not in itself a finding about the gene and the disease.
chondrosarcoma (9 papers, 2015 to 2022). A malignant cartilaginous matrix-producing mesenchymal neoplasm arising from the bone and soft tissue. "High resistin levels in human chondrosarcoma tissues have been linked to MMP-2 expression and r-resistin promoted invasiveness and MMP-2 expression in human chondrosarcoma cells in vitro mediated by AMPK and p38 MAPK." (PMID 29361725, 2018). "Table I summarizes the associations of resistin expression and various clinicopathological parameters of chondrosarcoma tissues." (PMID 25404641, 2015). "Our other research has identified that the adipokines resistin and leptin increase chondrosarcoma angiogenesis and metastasis via different miRNA–mRNA regulatory pathways." (PMID 36359873, 2022). "It appears that resistin acts via PI3K/Akt-dependent signaling pathway to increase the expression of VEGF-A in human chondrosarcoma cells." (PMID 30631040, 2019). "Our previous work indicates that resistin regulates metastasis in chondrosarcoma, enhancing chondrosarcoma cell migration by increasing levels of MMP-2 expression." (PMID 30631040, 2019). "Analysis of the tumor hemoglobin content revealed that resistin overexpression promoted chondrosarcoma-induced angiogenesis in vivo." (PMID 30631040, 2019). "In this study, we provide evidences that resistin induces VEGF-A production in human chondrosarcoma cells, and contributes to tumor angiogenesis by suppressing miR-16-5p expression through PI3K/Akt signaling pathway." (PMID 30631040, 2019). "In this study, our results suggest that higher levels of resistin expression are found in chondrosarcoma tissue than in normal cartilage." (PMID 30631040, 2019). "Our results demonstrate that resistin promotes VEGF-A expression by suppressing miR-16-5p in chondrosarcoma patients." (PMID 30631040, 2019). "We have previously reported that resistin enhances tumor metastasis and lymphangiogenesis in human chondrosarcoma cells." (PMID 30631040, 2019). "We have previously reported that inhibition of resistin reduces chondrosarcoma metastasis and lymphangiogenesis." (PMID 30631040, 2019). "Conversely, miR-16-5p expression was diminished by resistin-overexpressing human chondrosarcoma cells." (PMID 30631040, 2019). "It was reported that resistin promotes chondrosarcoma metastasis and MMP2 expression through activation of AMPK/p38 signaling pathway and down-regulation of miR-519d expression in mouse models." (PMID 26729407, 2016). "Herein, we found that the expression of resistin was higher in chondrosarcoma biopsy samples than in normal cartilage." (PMID 25404641, 2015). "Taken together, our results indicate that resistin promotes chondrosarcoma metastasis and MMP-2 expression through activation of the AMPK/p38 signaling pathway and down-regulation of miR-519d expression." (PMID 25404641, 2015). "Here, we found that the expression of resistin was higher in chondrosarcoma biopsy tissues than in normal cartilage." (PMID 25404641, 2015). "Our results indicated that resistin induced cell migration by activation of AMPK phosphorylation in human chondrosarcoma cells." (PMID 25404641, 2015). "In this study, we found that increased resistin expression strongly stimulates chondrosarcoma cell migration and metastasis." (PMID 25404641, 2015). "Taken together, high expressions of resistin and MMP-2, as well as reduced expression of miR-519d, were found to be associated with chondrosarcoma development and metastasis." (PMID 25404641, 2015). "This study characterized the effects of resistin on MMP-2 expression in human chondrosarcoma, which is known to be responsible for subsequent increased migration and metastasis." (PMID 25404641, 2015). "Resistin induced Transwell and wound healing migration of chondrosarcoma cells in a dose-dependent manner." (PMID 25404641, 2015).
chondrosarcoma (continued). "In human chondrosarcoma cells, resistin induced angiogenesis of endothelial progenitor cells via upregulating VEGF-A expression through PI3K/Akt/miR-16-5P/VEGF-A signaling pathway to promote chondrosarcoma metastasis." (PMID 35541892, 2022). "Upregulation of resistin expression promotes EPCs angiogenesis in chondrosarcoma." (PMID 30631040, 2019). "CM from resistin-treated chondrosarcoma cells enhanced migration and tube formation in EPCs." (PMID 30631040, 2019). "These combined results suggest that inhibition of resistin might be a valuable therapeutic strategy for chondrosarcoma." (PMID 30631040, 2019). "Directly applying resistin to chondrosarcoma cell lines (JJ012 and SW1353) promoted mRNA and VEGF-A protein expression in a concentration-dependent manner, while stimulating chondrosarcoma cell lines with resistin (30 ng/ml) facilitated VEGF-A expression in a time-dependent manner." (PMID 30631040, 2019). "In this study, we examined the relationship of resistin with VEGF-A expression and tumor angiogenesis, and further investigated the molecular mechanism underlying resistin-induced VEGF-A-dependent angiogenesis in chondrosarcoma microenvironment." (PMID 30631040, 2019). "We hypothesized that resistin would influence tumor angiogenesis in chondrosarcoma microenvironment." (PMID 30631040, 2019). "This study emphasizes the importance of resistin in chondrosarcoma angiogenesis and suggests that resistin may be a useful target in the management of chondrosarcoma." (PMID 30631040, 2019). "Chondrosarcoma is a highly malignant tumor known to frequently metastasize; however, the role of resistin in the metastasis of human chondrosarcoma is largely unknown." (PMID 25404641, 2015). "Moreover, resistin expression was found to be associated with clinical stage and metastasis, and stimulation of chondrosarcoma cells with resistin increased cell migration in a dose-dependent manner." (PMID 25404641, 2015). "Notably, inhibition of resistin reduces chondrosarcoma metastasis and lymphangiogenesis 32,36." (PMID 32226495, 2020). "It is unknown as to whether resistin affects human chondrosarcoma angiogenesis." (PMID 30631040, 2019). "Hence, we investigated whether resistin-increased migration of chondrosarcoma cells is mediated by AMPK." (PMID 25404641, 2015). "Therefore, targeting resistin or its signaling pathways may enable the development of novel molecular targeted treatments for chondrosarcoma." (PMID 25404641, 2015). "Therefore, resistin may represent a potential novel molecular therapeutic target in chondrosarcoma metastasis." (PMID 25404641, 2015). "When resistin-regulated angiogenesis was examined by the in vivo CAM assay, we observed that CM from the resistin-treated chondrosarcoma cells promoted vessel formation, which was diminished by miR-16-5p mimic." (PMID 30631040, 2019). "RT-qPCR analysis of resistin, MMP-2, and miR-519d performed in chondrosarcoma and normal samples showed a positive correlation between resistin and MMP-2; and negative correlations between resistin and miR-519d, MMP-2 and miR-519d." (PMID 25404641, 2015). "The expression levels of resistin and MMP-2 in chondrosarcoma and normal cartilage were detected by immunohistochemical staining." (PMID 25404641, 2015). "The protein expressions of resistin and MMP-2 in chondrosarcoma patients were found to be significantly higher than in normal cartilage." (PMID 25404641, 2015). "The expression of resistin was significantly correlated with VEGF-A levels, while the content of miR-16-5p was negatively correlated with the expression of resistin and VEGF-A in human chondrosarcoma specimens." (PMID 30631040, 2019). "Next, we evaluated resistin and VEGF-A expression in clinical chondrosarcoma samples." (PMID 30631040, 2019). "Moreover, treatment with resistin increased matrix metalloproteinase (MMP)-2 expression and promoted cell migration in human chondrosarcoma cells." (PMID 25404641, 2015).
chondrosarcoma (continued). "Similarly, in chondrosarcoma studies, resistin and VEGF-A expression were positively correlated, resistin and VEGF-A were negatively correlated with miR-16-5p, and resistin inhibited miR-16-5p expression through PI3K/Akt signaling to promote VEGF-A expression and angiogenesis." (PMID 35625769, 2022). "However, the effects of AMPK activation on resistin-mediated metastasis and MMP expression in human chondrosarcoma are currently unknown." (PMID 25404641, 2015). "In this study, whether miR-519d play a role in resistin-mediated metastasis was examined and found that resistin promotes tumor metastasis and MMP-2 expression by down-regulation of miR-519d expression through the AMPK/p38 signaling pathway in human chondrosarcoma." (PMID 25404641, 2015). "However, resistin did not affect the cell viability in human chondrosarcoma cells." (PMID 25404641, 2015). "However, the effects of resistin on chondrosarcoma migration are still not well recognized." (PMID 25404641, 2015). "We also found a positive correlation between resistin and VEGF-A expression, and a negative correlation between resistin and VEGF-A with miR-16-5p in chondrosarcoma patients." (PMID 30631040, 2019).
prostate carcinoma (9 papers, 2013 to 2025). A carcinoma that arises from epithelial cells of the prostate gland. "Therefore, we decided to evaluate whether resistin impacts other cellular processes associated with prostatic cancer progression." (PMID 38137922, 2023). "Other adipokines that have been shown to play a role in prostate cancer progression include apelin and resistin." (PMID 39596205, 2024). "In particular, in prostate cancer, the adipokines leptin, visfatin, and resistin have been related as promoters of various stages of tumor progression." (PMID 38137922, 2023). "Although the involvement of leptin and resistin in malignancies such as breast and prostate cancers has been extensively studied, very little is known about their role in melanoma growth and chemotherapeutic outcome." (PMID 29568521, 2018). "Additionally, in comparison to benign prostate hyperplasia, the increased level of resistin was observed in high-grade prostate cancer tissue." (PMID 39941741, 2025). "Additionally, the adipokine resistin induces prostate cancer migration, invasion, and proliferation." (PMID 39596205, 2024). "This highlights resistin as an important adipokine in prostate cancer progression and metastasis." (PMID 38137922, 2023). "Associated with this decrease is a significantly lower expression of adipocyte-related genes such as adiponectin, FABP4 and resistin, a result in agreement with previously reported evidence of prostate cancer cells invasion and destruction of adipocytes within a primary human bone marrow stroma." (PMID 24240026, 2013). "In vivo and in vitro models for prostate cancer suggest that diets containing walnuts and almonds may reduce the risk of prostate cancer through declines in plasma levels of IGF-1, resistin, LDL-cholesterol, oxidative stress, and inflammation, and increased expression of tumor suppressors." (PMID 36986173, 2023). "Furthermore, resistin can promote the proliferation of prostate cancer cells." (PMID 35453670, 2022). "Our group confirmed that exposure of PC3 cells to resistin increases the secretion level of MMP-2 and MMP-9 in the conditioned medium, favoring invasion in prostate cancer cells." (PMID 38137922, 2023). "The prostate cancer cell lines PC3 and DU145 expressed resistin which played a role in their proliferation." (PMID 30131543, 2018). "Likewise, resistin induces the activation of PI3K concomitant with the phosphorylation and activation of Akt, resulting in increased cell proliferation in prostate cancer cells." (PMID 38137922, 2023).
renal dysfunction (9 papers, 2012 to 2025). "An increase in the level of resistin by 1 mcg/mL was associated with an increased chance of having renal dysfunction by 0.2%." (PMID 37623488, 2023). "However, the clinical utility of resistin is moderated by significant heterogeneity influenced by comorbidities such as renal dysfunction, ethnic variations driven by genetic polymorphisms, and the specific cardiovascular disease subtype." (PMID 41347124, 2025). "Renal dysfunction independently elevates resistin concentrations, confounding its interpretation in patients with concomitant chronic kidney disease." (PMID 41347124, 2025). "Individuals with renal dysfunction have accumulated serum resistin levels, which is possibly due to reduced renal clearance." (PMID 32130282, 2020). "Regarding renal dysfunction and resistin levels, we found that serum resistin levels correlated with an increase in creatinine concentrations only in the entire group of SLE patients." (PMID 33133605, 2020). "Serum resistin levels were significantly increased in the subgroups with symptoms of cholestasis and renal dysfunction." (PMID 24259947, 2013). "However, its role is frequently confounded by comorbid conditions including renal dysfunction, which independently elevates circulating resistin concentrations." (PMID 41347124, 2025). "Therefore, we decided to assess the value of serum MIF, leptin, adiponectin and resistin levels as markers of proteinuria and renal dysfunction in LN." (PMID 33133605, 2020). "Indeed, resistin independently associates with decreases in glomerular function and increases in LVM are strongly associated with renal dysfunction beyond hemodynamic effects." (PMID 32000666, 2020). "In the present study we addressed the possibility that two important effects of resistin (increases in aortic stiffness or renal dysfunction) may explain the adverse cardiac actions of resistin." (PMID 32000666, 2020). "However, serum resistin levels are still significantly higher in patients with mild renal dysfunction than in those with eGFR> 90 mL/min/ 1.73 m2." (PMID 32130282, 2020). "Moreover, in both studies, the levels of resistin positively correlated with inflammatory markers, disease-specific measures and renal dysfunction." (PMID 22577940, 2012). "On the other hand, in the examination of renal dysfunction, we found that high MIF and resistin levels were correlated with an increase in serum creatinine in the entire SLE group." (PMID 33133605, 2020). "Independent relationships between circulating concentrations of the adipocytokine resistin and LVM are not explained by the impact of resistin on ventricular-vascular coupling or renal dysfunction." (PMID 32000666, 2020). "Thus, neither ventricular-vascular coupling nor renal dysfunction is likely to explain the relationships between circulating resistin concentrations and LV hypertrophy." (PMID 32000666, 2020).
vitamin D deficiency (9 papers, 2013 to 2025). A nutritional condition produced by a deficiency of VITAMIN D in the diet, insufficient production of vitamin D in the skin, inadequate absorption of vitamin D from the diet, or abnormal conversion of vitamin D to its bioactive metabolites. "The relationships between the principal adipokines (leptin, adiponectin, resistin) are revealed in the presence of normal vitamin D content and in vitamin D deficiency." (PMID 30881343, 2019). "In multivariate analysis, a CD4 count below 100/mm3, resistin concentration and being a smoker remained independently associated with severe vitamin D deficiency." (PMID 24058636, 2013). "Another study using an obese rat model showed that vitamin D deficiency exacerbates NAFLD through an increase of hepatic resistin and Toll-like receptor activation." (PMID 24130687, 2013). "The mean serum concentrations of leptin (P = 0.002), resistin (P = 0.037), and TNF-α (P < 0.001) were significantly higher in the cases with vitamin D insufficiency (cases) than those with vitamin D sufficiency (controls)." (PMID 36071429, 2022). "On the other hand, adjustment for resistin, IL-6, MCP-1 and TNF-α did not weaken the relationship between vitamin D deficiency and low CD4 counts." (PMID 24058636, 2013).
acute pancreatitis (8 papers, 2015 to 2024). An acute inflammatory process that leads to necrosis of the pancreatic parenchyma. "In a study of patients with acute pancreatitis, resistin levels upon admission were significantly linked to clinical severity and clinical endpoints such as death, serving as an early predictor of peripancreatic necrosis and acute pancreatitis severity." (PMID 37834432, 2023). "Recently, plenty of research papers have been conducted to explore the association between peripheral resistin and the severity of acute pancreatitis (AP)." (PMID 35770007, 2022). "Even though the mechanism underlying the effect of resistin in the aggravation of acute pancreatitis seems different from that of cerulein, these studies suggest that combined treatment of cerulein and resistin may augment severe acute pancreatic damage." (PMID 34349610, 2021). "A total of 7 of 10 studies showed significantly increased levels of resistin in patients with SAP relative to patients with mild acute pancreatitis (MAP)." (PMID 38218787, 2024). "Data were extracted to calculate the pooled Hedges' g and its 95% CI, which were selected to assess peripheral resistin levels and the severity of acute pancreatitis." (PMID 35770007, 2022). "Peripheral resistin levels were significantly increased in severe acute pancreatitis compared with mild acute pancreatitis (Hedges' g = 2.092, 95% CI: 0.994-3.190, P < 0.001)." (PMID 35770007, 2022). "Resistin levels are increased in the pancreatic tissues of patients with acute pancreatitis, and the increased expression of resistin correlates with the severity of acute pancreatitis." (PMID 34349610, 2021). "Higher circulating levels of resistin were shown in hospitalized patients with severe acute pancreatitis than healthy subjects." (PMID 34349610, 2021). "Resistin is known to have a proinflammatory potential since serum resistin levels increase in parallel with C-reactive protein in acute pancreatitis." (PMID 34349610, 2021). "It is necessary to determine the effect of resistin on pancreatic PGC-1α in the pathogenesis of acute pancreatitis for the further study." (PMID 34349610, 2021). "So there is a great stimulus to initiate a new study trying to find the relationship between resistin, peripancreatic necrosis, acute pancreatitis course, complications and outcomes." (PMID 27549125, 2016). "The aim of the present study was to detect the expression of resistin in rats with acute pancreatitis (AP) and investigate its significance in the pathogenesis of AP." (PMID 25780448, 2015). "Further studies are necessary to determine whether cerulein/resistin activates zymogen and increases digestive enzyme secretion in pancreas, which may contribute to development of severe acute pancreatitis." (PMID 34349610, 2021). "Since serum resistin levels are high in the patients with acute pancreatitis, increased levels of resistin have been used as an early marker of inflammation in patients with acute pancreatitis." (PMID 34349610, 2021). "Taken together, overproduction of resistin and accompanying inflammatory response may lead to the aggravation of severe acute pancreatitis, possibly with the accompanying organ failure." (PMID 34349610, 2021).